KCNAB2 (potassium voltage-gated channel subfamily A regulatory beta subunit 2)
Description:
Regulatory subunit of the voltage-gated potassium (Kv) Shaker channels composed of pore-forming and potassium-conducting alpha subunits and of regulatory beta subunits. The beta-2/KCNAB2 cytoplasmic subunit promotes potassium channel closure via a mechanism that does not involve physical obstruction of the channel pore. Promotes the inactivation of Kv1.4/KCNA4 and Kv1.5/KCNA5 alpha subunit-containing channels. Displays nicotinamide adenine dinucleotide phosphate (NADPH)-dependent aldoketoreductase activity by catalyzing the NADPH-dependent reduction of a wide range of aldehyde and ketone substrates (By similarity). Substrate specificity includes methylglyoxal, 9,10-phenanthrenequinone, prostaglandin J2, 4-nitrobenzaldehyde, 4-nitroacetophenone and 4-oxo-trans-2-nonenal (in vitro, no physiological substrate identified yet) (By similarity). The binding of oxidized and reduced nucleotide alters Kv channel gating and may contribute to dynamic fine tuning of cell excitability (By similarity). Contributes to the regulation of nerve signaling, and prevents neuronal hyperexcitability (By similarity).
Synonyms: hKvbeta2; KCNA2B; AKR6A5; HKvbeta2.1; HKvbeta2.2; KV-BETA-2
Tractability: Small molecule: a structure with a bound ligand is known; it has a high-quality binding pocket. Antibody: UniProt places it where antibodies can reach, with high confidence; its Gene Ontology location is reachable by antibodies, with high confidence. PROTAC: ubiquitination databases record sites on it; its protein half-life has been measured.
Target class: Enzyme; Oxidoreductase
Gene: Protein-coding gene on chromosome 1 (5,990,927 to 6,101,193, forward strand). Ensembl gene ENSG00000069424.
Subcellular location: Cytoplasm; Membrane; Cell membrane; Cell projection, axon; Synapse, synaptosome; Cytoplasm, cytoskeleton
Pathways (Reactome):
Immune System: Neutrophil degranulation
Neuronal System: Voltage gated Potassium channels
Gene Ontology:
Molecular function: potassium channel regulator activity; protein binding; alcohol dehydrogenase (NADP+) activity; methylglyoxal reductase (NADPH) (acetol producing) activity; transmembrane transporter binding; voltage-gated potassium channel activity
Biological process: regulation of potassium ion transmembrane transport; regulation of protein localization to cell surface; neuromuscular process; potassium ion transmembrane transport; potassium ion transport
Cellular component: juxtaparanode region of axon; membrane; voltage-gated potassium channel complex; cytoplasm; cytoplasmic side of plasma membrane; cytosol; microtubule; pinceau fiber; plasma membrane; specific granule membrane; tertiary granule membrane; axon; axon initial segment; axon terminus; cytoskeleton; postsynaptic density; synapse
Genetic constraint (gnomAD): Loss-of-function variants: 27 observed, 59.83 expected, observed/expected ratio (o/e) 0.45, 90% interval 0.33 to 0.62. The upper end of that interval is the gene's LOEUF score, 0.62, which puts it in group 2 of 6, group 1 being the genes least tolerant of losing a copy. Missense variants: 335 observed, 530.41 expected, observed/expected ratio (o/e) 0.63, 90% interval 0.58 to 0.69. Synonymous variants: 217 observed, 215.37 expected, observed/expected ratio (o/e) 1.01, 90% interval 0.9 to 1.13.
Homologues: Orthologues: chimpanzee KCNAB2 (100% identical), macaque KCNAB2 (100% identical), dog KCNAB2 (99% identical), pig KCNAB2 (99% identical), mouse Kcnab2 (98% identical), rat Kcnab2 (98% identical), tropical clawed frog kcnab2 (90% identical), zebrafish kcnab2a (87% identical), guinea pig KCNAB2 (84% identical), zebrafish kcnab2b (83% identical), rabbit KCNAB2 (72% identical), Caenorhabditis elegans Y39G8B.1 (17% identical), and 7 more. Paralogues in human: KCNAB1 (69% identical), KCNAB3 (62% identical), AKR1C2 (20% identical), AKR1B10 (20% identical), AKR1C3 (20% identical), AKR1C8 (20% identical), AKR1C1 (20% identical), AKR1C4 (20% identical), AKR1A1 (20% identical), AKR1B1 (20% identical), AKR7A2 (20% identical), AKR1D1 (19% identical), and 4 more.
Diseases named in the same sentence as KCNAB2 in open-access papers:
KCNAB2 is named in the same sentence as 25 diseases in open-access papers, as found by Europe PMC text mining. Sharing a sentence is not in itself a finding about the gene and the disease. The quoted sentences say what the papers report.
epilepsy (6 papers, 2008 to 2023). A brain disorder characterized by episodes of abnormally increased neuronal discharge resulting in transient episodes of sensory or motor neurological dysfunction, or psychic dysfunction. "The KCNAB2 (potassium voltage‐gated channel subfamily A regulatory beta subunit 2) gene has been associated with epilepsy in 1p36DS, and a recent study also supports this hypothesis." (PMID 36369750, 2023). "The KCNAB2 gene encodes voltage-gated K+ channel beta-subunit, and the decrease of its expression will reduce membrane repolarization, leading to a reduction of the threshold of epilepsy." (PMID 32655475, 2020). "Therefore, haploinsufficiency of KCNAB2 was suggested as a significant risk factor for epilepsy." (PMID 29554876, 2018). "In a study of individuals with 1p36 deletion syndrome, eight out of nine (89%) patients with hemizygous deletions of KCNAB2 (which resides in the deleted region) also had epilepsy or epileptiform activity on electroencephalogram." (PMID 29554876, 2018). "An epilepsy candidate gene KCNAB2 was found to be deleted in the majority of seizure prone 1p36 patients, and human gamma-aminobutyric acid A receptor delta-subunit gene (GABRD) has been implicated in abnormal neurodevelopment." (PMID 19019217, 2008). "Five out of 10 patients with deletions including both GABRD and KCNAB2 had epilepsy in our cohort." (PMID 36369750, 2023).
lung carcinoma (3 papers, 2022 to 2025). "As a member of the Kvβ superfamily, KCNAB2 has been reported to inhibit the proliferation and metastasis of lung cancer." (PMID 41343099, 2025). "The proliferation and migration ability of lung cancer cells was altered after KCNAB2 overexpression by plasmid transfection, although the difference is not statistically significant." (PMID 37852974, 2023). "Nomogram model suggests a good reliability of KCNAB2 in predicting prognosis of lung cancer patients." (PMID 37852974, 2023). "More interactive research is required to comprehend how KCNAB2 overexpression in lung cancer cells influences the patterns of immune cell infiltration." (PMID 36359834, 2022).
neuroblastoma (3 papers, 2017 to 2023). Neuroblastoma (NB) is the most common solid, extracranial childhood tumor. "According to several studies, KCNAB2 may play a role in the occurrence and progression of neuroblastoma, glioblastoma multiforme, pituitary tumor, and lymphoma." (PMID 36359834, 2022). "Some studies have found that KCNAB2 may be involved in the occurrence and development of lymphoma, colorectal cancer, pituitary tumor, and neuroblastoma, but its role in lung adenocarcinoma remains unknown." (PMID 36359834, 2022).
glioblastoma (2 papers, 2022 to 2025). The most malignant astrocytic tumor (WHO grade IV). "Glioblastoma studies included E5 (KCNJ10, KCNN3), E21 (KCNAB2), E26 (KCNE2, KCNJ13), E27 (KCNE4, KCNMB2-AS1), E31 (KCNJ10), E50 (KCND3), and E51 (KCNIP1, KCNJ16, KCNN2)." (PMID 40867621, 2025).
lung adenocarcinoma (2 papers, 2022 to 2023). A carcinoma that arises from the lung and is characterized by the presence of malignant glandular epithelial cells. "Receiver operating characteristic (ROC) curve results reveal that KCNAB2 downregulation has a significant predictive value on poor survival probability of patients with lung adenocarcinoma and lung squamous cell carcinoma." (PMID 37852974, 2023). "At the same time, we also examined the effect of KCNAB2 on the functional status of lung adenocarcinoma cells." (PMID 36359834, 2022). "The findings demonstrated that, compared with normal tissues, lung adenocarcinoma had considerably decreased protein expression of KCNAB2." (PMID 36359834, 2022). "It is worth noting that KCNAB2 does not seem to have a significant effect on the functional status of lung adenocarcinoma cells themselves, as predicted from the cancerSEA database, which motivates us to explore the effect of KCNAB2 on the tumor microenvironment." (PMID 36359834, 2022). "Finally, KCNAB2 was overexpressed in lung adenocarcinoma cell lines (A549 and H23) to investigate its potential biological function." (PMID 36359834, 2022).
lung squamous cell carcinoma (2 papers, 2022 to 2023). "First, the diagnostic and prognostic usefulness of KCNAB2 in lung squamous cell carcinomas (LUSC), large cell lung carcinomas (LCLC), and small cell lung carcinomas (SCLC) was not examined in this investigation." (PMID 36359834, 2022).
non-small cell lung carcinoma (2 papers, 2023 to 2025). A group of at least three distinct histological types of lung cancer, including non-small cell squamous cell carcinoma, adenocarcinoma, and large cell carcinoma. "Interestingly, FTO-catalyzed m6A modification of potassium voltage-gated channel subfamily A regulatory beta subunit 2 (KCNAB2) is implicated in non-small cell lung cancer progression." (PMID 40986143, 2025).
clear cell renal cell carcinoma (1 paper, 2022). "KCNAB2 achieves high protein expression, and its high mRNA level is confirmed to be an unfavorable prognostic marker in clear cell renal cell carcinoma (ccRCC) tissues." (PMID 36789694, 2022).
Colon Cancer (1 paper, 2021). "Based on these in-silico results, we investigated the potential role of KCNAB2 in tumor cell proliferation using two commercial colon cancer cell lines were used, in particular, HT29 and SW480 cells." (PMID 33802791, 2021).
colorectal cancer (1 paper, 2022). A primary or metastatic malignant neoplasm that affects the colon or rectum. "The evidence demonstrated that voltage-gated potassium channel subunit beta-2 (KCNAB2) significantly participated in the initiation of colorectal cancer and its progression." (PMID 36359834, 2022).
heart failure (1 paper, 2020). Inability of the heart to pump blood at an adequate rate to meet tissue metabolic requirements. "Finally, CACNB2, KCNAB2, and TIMM22 encode subunits that participate in dysfunctional voltage-gated channels that may be associated with arrhythmia events rather than aggravated heart failure." (PMID 32802835, 2020).
mucinous adenocarcinoma (1 paper, 2023). An invasive adenocarcinoma composed of malignant glandular cells which contain intracytoplasmic mucin. "The cg01907457 site on the KCNAB2 gene has the most differential methylation level between the GC subtypes papillary adenocarcinoma NOS and mucinous adenocarcinoma." (PMID 36827074, 2023).
papillary adenocarcinoma (1 paper, 2023). A morphologic variant of adenocarcinoma. "We found that cg05307871 on the KCNAB2 gene has the most differential methylation level between the GC subtypes papillary adenocarcinoma NOS and carcinoma diffuse type." (PMID 36827074, 2023).
renal carcinoma (1 paper, 2022). A carcinoma arising from the epithelium of the renal parenchyma or the renal pelvis. "In brief, KCNAB2 and GAPDH could act as candidate biomarkers to identify patients suffering from renal cancer and even early renal cancer." (PMID 36789694, 2022).
Seizure (1 paper, 2007). A seizure is an intermittent abnormality of nervous system physiology characterized by a transient occurrence of signs and/or symptoms due to abnormal excessive or synchronous neuronal activity in the brain. "Seizures and a reduced lifespan have also been described in Kcna1 null mice, in which the expression of the Kv1.1 subunit is abolished, as well as in Kcnab2 null mice, lacking the modulatory subunit beta 2, which co-distributes extensively with Kv1.1 and Kv1.2 in the adult rat brain." (PMID 17925011, 2007).
tumor (7 papers, 2018 to 2023). "Tumor growth curve results demonstrated that, as compared to control A549 xenografts, KCNAB2-overexpressed xenografts grew slower." (PMID 37852974, 2023). "We subcutaneously injected equal amounts of KCNAB2-overexpressed A549 cells (“KCNAB2-OE”) along with vector control cells (“Vec”) in the right flanks of nude mice to establish tumor xenografts." (PMID 37852974, 2023). "Based on cancer TNM stage, patients from various groups had significantly lower KCNAB2 expression levels in tumor tissues compared with normal tissues." (PMID 36359834, 2022). "Next, we assessed the relationship between KCNAB2 and immune infiltration using ssGSEA to further evaluate the impact of KCNAB2 on the tumor microenvironment." (PMID 36359834, 2022). "The findings demonstrated that KCNAB2 expression was considerably increased in nine tumor tissues and decreased in eight tumor tissues, as compared with normal tissues." (PMID 36359834, 2022). "After accounting for tumor purity, KCNAB2 expression was shown to be substantially correlated with the majority of immunological markers in various immune cell types in LUAD." (PMID 36359834, 2022). "For the first time, our investigation revealed a strong positive connection between KCNAB2 expression and the tumor infiltration of 18 immune effector cells from the innate and adaptive immune systems." (PMID 36359834, 2022). "We used the TIMER database to identify the expression connection of KCNAB2 with immune cell biomarkers in LUAD in order to further investigate the function of KCNAB2 in tumor immunity." (PMID 36359834, 2022). "Whether tumor cells overexpressing KCNAB2 can predominantly recruit fragile Treg or whether the secreted cytokines can drive the fragile phenotype of Treg are questions that need to be further explored." (PMID 36359834, 2022). "We lack direct evidence of KCNAB2 being involved in tumor immune infiltration." (PMID 36359834, 2022). "Furthermore, out of 30 pairs of samples, 27 pairs (90%) had significantly higher levels of KCNAB2 protein in tumor tissues than in matched normal tissues." (PMID 36789694, 2022). "Additionally, we investigated possible evidence indicating that KCNAB2 affects the infiltrating level of immune cells in the tumor environment of patients with LUAD." (PMID 36359834, 2022). "In particular, the GSE34053 dataset analyzed cancer-associated fibroblasts (CAF, tumor stromal cells) and CD133+ cells (tumor epithelial cells); while CD133+ cells expressed higher levels of KCNAB2 and KCNMB4, CAF cells (stroma) overexpressed SCN9A and KCNJ8 subunit channels." (PMID 33802791, 2021). "Furthermore, Ki67 decrease was also detected in KCNAB2-overexpressed A549 xenograft tumor tissues." (PMID 37852974, 2023). "In the tumor tissues of patients with LUAD from various age groups, there was a markedly reduced KCNAB2 level according to age." (PMID 36359834, 2022). "Further research on KCNAB2 protein expression in LUAD tissues using IHC staining revealed that, in contrast to normal lung tissues, the KCNAB2 protein level was clearly lower in tumor tissues." (PMID 36359834, 2022). "However, the biological function of KCNAB2 in LUAD and its effect on the tumor immune microenvironment are still unknown." (PMID 36359834, 2022).
cancer (6 papers, 2021 to 2023). A tumor composed of atypical neoplastic, often pleomorphic cells that invade other tissues. "First, the mRNA expression level of KCNAB2 in various cancers was detected using the TIMER online database." (PMID 36359834, 2022). "In this study, we found that the expression of KCNAB2 in tissues of patients with LUAD was markedly downregulated, and its downregulation was linked to accelerated cancer growth and poor clinical outcomes." (PMID 36359834, 2022). "Chemokines are important to the migration of immune cells, so we explored how KCNAB2 interacts with chemokines that are relevant to cancer immunity." (PMID 36359834, 2022). "While we did not evaluate the level of autoantibodies against KCNAB2 and GAPDH in sera of other types of cancer, referring to published results of screening autoantibodies based on proteome microarrays for a variety of tumors, autoantibodies against KCNAB2 and GAPDH seems to be specific in ccRCC." (PMID 36789694, 2022). "In addition to this, we also examined the effect of KCNAB2 on the functional status of the cancer cells." (PMID 36359834, 2022). "Therefore, these discoveries have the potential to further our understanding of KCNAB2’s function as well as its prospective use in cancer immunotherapy and prognosis." (PMID 36359834, 2022). "Our research highlights KCNAB2’s prominent function in the development of cancer and suggests that it may be crucial for regulating immune cell infiltration in LUAD." (PMID 36359834, 2022). "We thus detected the connections between KCNAB2 expression and cancer-related chemokines." (PMID 36359834, 2022). "In this context, KCNAB2, H2AFY, DOCK2 and GSTM1 in our signature significant high expression in high‐risk group compare to low‐risk group and related to poor prognosis, and all genes except KCNAB2 in signature have been reported to be involved in cancer." (PMID 33259129, 2021). "KCNAB2 in our mRNA signature almost never be reported in cancer pathogenesis or disease progression may be due to its tissue specificity." (PMID 33259129, 2021). "We chose to carry out a completely integrated bioinformatics study to pinpoint the KCNAB2 gene’s related functions and pathways in LUAD, because there had not been many studies on this gene’s role in cancer." (PMID 36359834, 2022).
psychiatric disorder (1 paper, 2016). A disorder characterized by behavioral and/or psychological abnormalities, often accompanied by physical symptoms. "Seizure-related disorders and their subsequent behavioral symptoms caused by dyfunctions of the central nervous system are often linked with psychiatric disorders, providing clues for the roles of KCNAB2 in neurological and psychiatric disorders." (PMID 27450446, 2016).
KCNAB2 also shares sentences with these, for which no sentence is quoted: and retinal (1 paper); large cell lung carcinomas (1); lymphoma (1); memory impairment (1); pituitary adenoma (1); pituitary tumor (1); small cell lung carcinoma (1).